IGF1 (insulin like growth factor 1)
Diseases named in the same sentence as IGF1 in open-access papers (continued):
Sharing a sentence is not in itself a finding about the gene and the disease.
Proptosis (1 paper, 2024). An eye that is protruding anterior to the plane of the face to a greater extent than is typical. "Of the 11 patients included in this study, case 8 had mild proptosis, which was not treated with ATD, after GH/IGF-1 levels decreased after TSS and SSA treatment, the symptoms of proptosis improved." (PMID 38349236, 2024).
pulmonary embolism (1 paper, 2018). The obstruction of the pulmonary artery or one of its branches by an embolus, sometimes associated with infarction of the lung. "A treatment regimen composed of repeated intravenous injections of MSCs or MSC_IGF-1 was associated with increased mortality (40% for the MSC group and 30% for the MSC_IGF-1 group) in mice chronically infected with T. cruzi, due to pulmonary embolism." (PMID 30140292, 2018).
R6 (1 paper, 2014). "In this regard, IGF-1 levels have been shown to decrease in an age-dependent manner in the R6/2 HD mouse model, associating IGF-I levels with the body weight loss that occurs in HD patients." (PMID 25140802, 2014).
Renal artery stenosis (1 paper, 2025). The presence of stenosis of the renal artery. "Additional factors implicated in its development include insulin-like growth factor-1 (IGF-1) and its binding proteins, activation of the angiotensin-II receptor, renal artery stenosis, and endogenous androgens." (PMID 40255807, 2025).
Renal cyst (1 paper, 2016). A fluid filled sac in the kidney. "On the other hand, IGF-1 could play a pathogenic role in hyperplasia of renal tubular epithelial cells and in the formation of renal cysts as it contributes to compensatory renal growth and may modestly contribute to progressive glomerular sclerosis." (PMID 26990190, 2016).
Respiratory distress (1 paper, 2024). Respiratory distress is objectively observable as the physical or emotional consequences from the experience of dyspnea. "IGF‐1 dysregulations have been associated with alveolar hyperplasia and lethal neonatal respiratory distress." (PMID 38344410, 2024).
respiratory infections (1 paper, 2021). "In both mouse models and premature human infants reduced IGF-1 concentrations were associated with disrupted lung development, which in turn was thought to have an enduring effect on host resistance to respiratory infections." (PMID 33540923, 2021).
restrictive lung disease (1 paper, 2025). "High levels of GH/IGF-1 have a simultaneous proliferative effect on lung growth and a degenerative effect on smooth muscle, leading to a mixed obstructive and restrictive lung disease." (PMID 41589173, 2025).
retinal oedema (1 paper, 2025). "Similarly, IGF-I and IGF-I receptors are expressed in the mammalian retina, and in primary cultures the treatment with IGF-1 has been demonstrated to determine mild, generalized, and reversible retinal oedema." (PMID 41071261, 2025).
retinitis pigmentosa (1 paper, 2022). Retinitis pigmentosa (RP) is an inherited retinal dystrophy leading to progressive loss of the photoreceptors and retinal pigment epithelium and resulting in blindness usually after several decades. "IGF-1 is an important pro-survival signal for photoreceptors and protects photoreceptors from apoptosis in the context of retinitis pigmentosa (RP)." (PMID 35356301, 2022).
ROHHAD syndrome (1 paper, 2014). "On the other hand, in patients with ROHHAD syndrome, IGF-1 levels and response to GH stimulatory tests are low." (PMID 25541898, 2014).
sensory impairment (1 paper, 2017). "As pari passu circulating insulin-like growth factor 1 (IGF-1) bioavailability progressively decreases, we see a direct correlation with sensory impairment and cognitive performance in older humans." (PMID 29311900, 2017).
silicosis (1 paper, 2018). Silicosis is a respiratory disease caused by breathing in (inhaling) silica dust. "IGF-1 is released by quartz dust-exposed human macrophages as a result of phagocytosis in vitro, serving as a paracrine mitogen for human fibroblasts, ATII, and tracheobronchial epithelial cells, which is suggested to be involved in the epithelial repair and hyperplasia observed in silicosis." (PMID 30018981, 2018).
sleep-wake disorder (1 paper, 2024). Abnormal sleep-wake schedule or pattern associated with the circadian rhythm which affect the length, timing, and/or rigidity of the sleep-wake cycle relative to the day-night cycle. "Behavioral symptoms of circadian rhythm imbalance and sleep-wake disorders were noted to be improved by increasing or releasing free IGF1 in serum." (PMID 38800060, 2024).
SOFT syndrome (1 paper, 2024). "A state of resistance to IGF1, as attested by high IGF1 serum levels in several patients with SOFT syndrome, may also contribute to growth retardation." (PMID 39017987, 2024).
solitary fibrous tumor (1 paper, 2023). Solitary fibrous tumor (SFT) represents a diverse group of ubiquitous rare spindle cell neoplasms that may be benign or malignant and that most frequently arises from the pleura and peritoneum and rarely from other sites such as head and neck, liver and skeletal muscle. "Further workup revealed low insulin, C-peptide, and IGF-1 levels and a large right in-trathoracic solitary fibrous tumor." (PMID 37357513, 2023).
spasm (1 paper, 2024). "Compared to the tumor control tissue, we observed a dramatic decrease in the expression of GAD, PV, and IGF-1 in spasm patients, marked by a decrease in the density of putative GABAergic nerve terminals." (PMID 39516073, 2024).
Spherocytosis (1 paper, 2014). The presence of erythrocytes that are sphere-shaped. "However, this represents the first report of low IGF-1 levels among spherocytosis patients." (PMID 25299063, 2014).
squamous cervical cancer (1 paper, 2015). "The present study aimed to analyze the association between the CA dinucleotide repeat length polymorphism in the P1 promoter region of the IGF-1 gene in the peripheral blood cells and cervical tissue samples of females with SILs of the uterine cervix and squamous cervical cancer." (PMID 25384883, 2015).
Stuve-Wiedemann syndrome (1 paper, 2023). "Abbreviations: SWS = Stuve-Wiedemann syndrome, IVCM = in vivo confocal microscopy, CNTF = ciliary neurotrophic factor, BCVA = best corrected visual acuity, LIFR = Leukemia Inhibitory Factor Receptor, IGF1 = Insulin-like growth factor-1." (PMID 38239413, 2023).
systolic heart failure (1 paper, 2016). Heart failure caused by abnormal myocardial contraction during systole leading to defective cardiac emptying. "Previous studies demonstrated the prognostic value of IGFBP-7 and IGF-1 among patients with systolic heart failure (HF)." (PMID 27769173, 2016).
testicular germ cell tumours (1 paper, 2019). "In accordance with other tumour types, height has also been reported as a risk factor for testicular germ cell tumours (TGCTs), although there is no direct evidence that circulating IGF1 levels are linked to a higher risk of developing TGCT." (PMID 31179642, 2019).
thymic epithelial tumors (1 paper, 2014). "The expression of insulin-like growth factor 1 in thymic epithelial tumors is associated with prognosis in these patients." (PMID 25013463, 2014).
thymoma (1 paper, 2023). A neoplasm arising from the epithelial cells of the thymus. "In a patient with acromegaly and a thymoma, the surgical removal of the GH-producing tumor resulted in a reduction in the size of the thymoma along with a decrease in plasma IGF-1 levels." (PMID 38201593, 2023). "Higher expressions of SOX2 and IGF-1 proteins were markedly elevated in thymic carcinomas compared to thymomas, as observed through immunohistochemistry." (PMID 38201593, 2023).
tonsillitis (1 paper, 2016). Inflammation of the tonsillar tissue. "This study aimed to determine the effect of adenotonsillectomy on IGF-1 and IGFBP-3 serum levels in patients with ATH or recurrent tonsillitis." (PMID 27738609, 2016).
Tourette syndrome (1 paper, 2016). A neurologic disorder caused by defective metabolism of the neurotransmitters in the brain. "Thus, deficiency of IGF-1+ microglia in this animal model of Tourette syndrome might lead to impaired neuroprotection and, consequently, to enhanced susceptibility to neuroinflammation after an environmental challenge." (PMID 28053994, 2016). "We have found reduced IGF-1 expressing microglia in the striatum in the Hdc-KO model of Tourette syndrome pathophysiology." (PMID 28053994, 2016).
toxoplasmosis (1 paper, 2019). A parasitic disease contracted by the ingestion or fetal transmission of toxoplasma gondii. "We speculate that intraocular blockade of VEGF and/or IGF1, and/or supplementation with TSP1, might have a therapeutic application for limiting the extent of the ocular lesion in toxoplasmosis." (PMID 31569536, 2019).
transient cerebral ischemia (1 paper, 2005). "Bolus injections into one lateral ventricle of IGF-1 have been reported, for instance, to improve neurological outcome for both permanent and transient cerebral ischemia in rats and other small laboratory animals." (PMID 16045806, 2005).
vitamin B12 deficiency (1 paper, 2022). A disease characterized by low serum levels of vitamin B12, either inherited or acquired. "As first vitamin B12 deficiency may impact directly on taurine synthesis and insulin-like growth factor 1(IGF-1) production." (PMID 35992115, 2022).
vitamin C deficiency (1 paper, 2021). "We observed that chronic vitamin C deficiency in young (8-9 months old) and old (2 years old) mice has more pronouncing effects on serum IGF-1 levels." (PMID 34221500, 2021). "In our study, the changes of free IGF-1 induced by vitamin C deficiency may play a role in regulating LDL and h-apo(a) metabolism." (PMID 34221500, 2021). "We observed that chronic vitamin C deficiency resulted in a less healthy metabolic lipid profile, impaired serum insulin-like growth factor (IGF-1), and sex-hormones secretion, all of which can accelerate the development of various pathological conditions in the aging process." (PMID 34221500, 2021). "In conclusion, our study shows that chronic vitamin C deficiency results in a negative impact on lipid metabolic profile, testosterone and estradiol levels, and IGF-1 regulations in Gulo (−/−) and Lp(a)+ mice throughout the aging process." (PMID 34221500, 2021).
Weaver syndrome (1 paper, 2024). Weaver syndrome (WVS) is a rare, multisystem disorder characterized by tall stature, a typical facial appearance (hypertelorism, retrognathia) and variable intellectual disability. "Analyses of a mouse-model for Weaver syndrome (wv) suggest that IGF-1 serum levels play an important role in postnatal growth during and after neurodegeneration of wv mice and that IGF-1’s regulation of systemic growth during and after puberty is likely modulated by androgen in male wv mice." (PMID 38894719, 2024).
X-linked hypophosphatemia (1 paper, 2024). X-linked hypophosphatemia (XLH) is a hereditary renal phosphate-wasting disorder characterized by hypophosphatemia, rickets and/or osteomalacia, and diminished growth. "In the X-linked hypophosphatemia population, the increase in serum P level after GH treatment may be related to IGF-1." (PMID 38732596, 2024).
xerostomia (1 paper, 2009). Dryness of the mouth resulting from reduced salivary secretion. "Targeted delivery of IGF1 to the salivary gland of patients receiving head and neck irradiation may be useful in reducing or eliminating xerostomia and restoring quality of life to these patients." (PMID 19252741, 2009).
ZIKV infection (1 paper, 2022). "Most importantly, the similarities of growth defects caused by chico mutations in Drosophila and insulin/IGF1 signaling pathway in vertebrates suggest that this pathway, chico in particular, plays a conserved role in antiviral immunity and metabolism during ZIKV infection." (PMID 35844546, 2022).
cancer (2,223 papers, 1997 to 2026). A tumor composed of atypical neoplastic, often pleomorphic cells that invade other tissues. "Both GH and IGF-1 are implicated in cancer promotion based on experimental and epidemiological data, but research findings remain conflicting and population-based data are scarce." (PMID 41753260, 2026). "Cancer-associated fibroblasts in the cavernous sinus secrete IGF1 under regulation of the transcription factor FOXO1, which binds to receptors on tumor cells to activate proliferation." (PMID 42119924, 2026). "By downregulating IGF-1, fasting creates a metabolic environment where cancer cells are more susceptible to apoptosis." (PMID 39940361, 2025). "Animal studies confirm that reduced IGF-1 levels are associated with decreased tumor growth, further supporting the role of IGFs in cancer progression." (PMID 40723309, 2025). "A large UK Biobank cohort study (n = 412,645; median follow-up 7.2 years) found that elevated circulating IGF-1 levels were associated with an increased overall cancer risk." (PMID 41367907, 2025). "While IGF-1 is beneficial for vascular health, there are significant concerns regarding its use as a treatment due to its association with increased cancer risk." (PMID 39271571, 2025). "In both BC and other cancer contexts, elevated levels of insulin and IGF-1 have been implicated in tumorigenesis via activation of mitogenic and anti-apoptotic signaling pathways, such as Ras-MAPK and PI3K-Akt." (PMID 40731797, 2025). "As a growing number of studies have sought to decipher the molecular mechanisms underlying the association of IGF1 systems with EC, the AS of IGF1 has emerged as the current area of cancer research interest." (PMID 39796756, 2025). "Tumor-stroma single-cell transcriptomics pinpointed cancer-associated fibroblasts (CAFs) as the dominant source of IGF1." (PMID 41275311, 2025). "Dysregulation of the IGF1 pathway has been implicated in tumorigenesis and progression across multiple cancer types by promoting cell proliferation and inhibiting apoptosis." (PMID 41333209, 2025). "In contrast, a tumor stroma enriched with mesenchymal cytokines like C-X-C motif chemokine 12 (CXCL12) and insulin-like growth factor 1 (IGF1) predisposes primary cancer cell population to home into the bone marrow." (PMID 41223092, 2025). "Dietary interventions, on the other hand, offer promising strategies to modulate insulin and IGF-1 signaling and reduce cancer risk." (PMID 40428567, 2025). "Elevated circulating levels of insulin and IGF-1 have been associated with increased tumorigenesis in several types of cancer, including breast, prostate, and colorectal cancers." (PMID 41008741, 2025). "Intriguingly, cancer‐associated fibroblasts‐secreted IGF‐1 upregulates QSOX2 expression via IGF1R/Akt/mTOR/c‐Myc pathway, establishing a positive feedback loop that sustains ESCC cell stemness." (PMID 40433832, 2025). "IGF-1 also influences cancer risk: men with high serum IGF-1 have increased risk of PCa development and lethality, with evidence of a causative association." (PMID 41184420, 2025). "These compounds, often found in plastic bottles, can dysregulate the IGF-1 axis and exhibit anti-estrogenic or anti-androgenic effects, further contributing to cancer risk." (PMID 40014232, 2025). "This condition not only precedes T2DM but is also a known risk factor for cancers, such as those of the prostate, colon, kidneys, and endometrium, driven by increased IGF-1 and insulin." (PMID 40014232, 2025). "Several studies since 1950 have implicated both GH and IGF-1 in the pathogenesis of several cancers and shown that the removal of their actions can significantly reduce and/or inhibit disease progression." (PMID 41515995, 2025). "More recently, a study involving nearly 400,000 participants confirmed an association between elevated blood IGF-1 levels and an increased risk of multiple cancer types, further emphasizing the link between IGF-1 levels and cancer risk." (PMID 39940361, 2025).
cancer (continued). "High levels of IGF-1 have been associated with increased risks of various cancers, including breast, prostate, and colorectal cancers." (PMID 39940361, 2025). "Given the established role of IGF-1 in breast tissue proliferation, clarifying this potential association has important clinical implications for cancer surveillance in this population." (PMID 41293738, 2025). "Elevated IGF-1 levels have been linked to increased cancer risk, particularly for cancers such as breast, prostate, and colon cancers (see Section 2.3.1)." (PMID 39940361, 2025). "High glycemic load diets, which rapidly raise blood glucose and insulin levels, have been associated with increased cancer risk, while calorie restriction has been shown to reduce insulin and IGF-1 levels, potentially slowing tumor growth." (PMID 40428567, 2025). "Elevated insulin and IGF-1 are associated with increased cell growth and proliferation, while metformin’s influence on these pathways parallels CR’s ability to reduce cancer-promoting signals." (PMID 39940361, 2025). "IGF-1 is a potent growth factor that can promote cellular proliferation, and elevated levels have been linked to the growth of certain cancers." (PMID 39271571, 2025). "Key metabolic pathways are tightly linked to cancer development, including insulin signaling, insulin‐like growth factor‐1 (IGF‐1), and mTOR." (PMID 40777199, 2025). "Previous studies have shown that high levels of IGF-1 are associated with an accelerated rate of aging and a high risk of cancer and metabolic diseases." (PMID 40137116, 2025). "Many population studies have indicated the correlation between the level of insulin and IGF1 and the risk of certain cancers." (PMID 39940361, 2025). "A low-protein diet has been associated with reduced IGF-1 levels in patients aged 50–65 years, subsequently decreasing their risk of death from cancer." (PMID 38462638, 2024). "High levels of IGF-1 have been associated with an increased risk of certain cancers, including breast and prostate cancer." (PMID 38313941, 2024). "This decrease leads to higher levels of unbound IGF-1 in cells and tissues, which is closely linked to a higher risk of cancer." (PMID 39429275, 2024). "Epidemiological studies found an association between high-normal levels of insulin, C-peptide, and IGF-1 with an increased risk of various cancers (such as breast, colon, and prostate)." (PMID 39434861, 2024). "In his study, gases were found to stimulate olfactory neurons, prompting other cells in the olfactory bulb to release IGF1, which in turn can stimulate the division of OPCs harboring pro‐cancer mutations." (PMID 39469896, 2024). "As in the cases of other cancers, increased serum levels of IGF-1, IGF-1R, and IGFBP-2 were also associated with EOC tumorigenesis." (PMID 38392069, 2024). "On the other hand, high levels of IGF-1/2 are linked to a higher risk of cancer and a lower lifespan." (PMID 38540176, 2024). "A cohort study specifically examined the effects of metformin, insulin, and sulfonylureas on the risk of developing GC and found that the latter two drugs actually increased the risk of GC by elevating the levels of IGF-1, which promotes cancer cell survival." (PMID 38612893, 2024). "IGF1/IGF1R pathway has been implicated in various aspects of cancer biology, such as cell transformation, EMT induction, invasion or metastasis, making it a desirable oncology therapeutic target." (PMID 39075581, 2024). "Elevated IGF-1 levels have been associated with a heightened cancer risk, making patients with T2DM more prone to developing various malignancies compared to healthy individuals." (PMID 39335195, 2024). "Recently, it was shown that IGF-1 is inversely associated with E-cadherin expression in various types of cancers." (PMID 39109301, 2024).